EGF (epidermal growth factor)
Diseases named in the same sentence as EGF in open-access papers (continued):
Sharing a sentence is not in itself a finding about the gene and the disease.
prostate carcinoma (continued). "EGF treatment upregulated phospho-YB-1 expression in a time-dependent manner, while treatment with an ERK inhibitor completely silenced its expression in prostate cancer cells." (PMID 34696665, 2021). "EGF is known to activate AKT in many epithelial cancer types, including prostate cancer." (PMID 34706306, 2021). "In prostate cancer, δ-catenin can stabilize EGFR to enhance EGF signaling." (PMID 34069970, 2021). "Then endogenous androgen signaling in hormone dependent prostate cancer cells resulted in the decreased TGF-β and activated EGF signaling, which could ultimately enhance the expression of PMEPA1 gene." (PMID 32064040, 2020). "EGF induces migratory behavior in prostate cancer cells (PC3 and DU145), and these effects are not inhibited by pretreatment of the cells by PT." (PMID 32575572, 2020). "In addition, higher expression of SERCA2b in the presence of growth factors such as EGF, DHT (dihydrotestosterone) serum, and the ER-Ca2+-pool concentration is important in regulating proliferation of LNCaP human prostate cancer cells." (PMID 31226817, 2019). "Quercetin prevented epidermal growth factor (EGF)-induced EMT via the epidermal growth factor receptor /P13K/Akt/extracellular signal-regulated kinase 1/2 pathway and by suppressing transcription factors, Snail, Slug and Twist, in PC-3 prostate cancer cells." (PMID 30708951, 2019). "Moreover, release of the transmembrane protein with EGF and two follistatin motifs (TMEFF2) increases prostate cancer cell motility." (PMID 30188954, 2018). "In prostate cancer, the acquired mesenchymal spindle-like cell structure, the increased expression of fibronectin and N-cadherin, and the E-cadherin concurrent decrease, represent the specific traits of EMT induced by EGF." (PMID 28430640, 2017). "Moreover, in prostate cancer cells Snail knockdown significantly reverses HLA-I downregulation induced by TGF-β and EGF, confirming that Snail is crucial for this process." (PMID 28430640, 2017). "Our results support a regulatory axis whereby CXCR7 is upregulated in the absence of AR signaling, which drives alternative EGF-mediated cell survival signaling, leading to androgen-independent prostate cancer progression." (PMID 28596572, 2017). "Notably, PKN1 regulates endometrial cancer cell proliferation by modulating TGFβ and epidermal growth factor (EGF) dependence, promotes prostate cancer cell proliferation through WDR5 (WD repeat-containing protein 5)." (PMID 28222172, 2017). "Further studies revealed that niclosamide blocked acidic pHe, HGF, and epidermal growth factor (EGF)-induced anterograde lysosome redistribution, protease secretion, motility, and invasion of DU145 castrate resistant prostate cancer cells at clinically relevant concentrations." (PMID 26784896, 2016). "It is also unclear at this point whether FFAR activation directly influences EGF-mediated signaling, or whether FFARs act indirectly via interference with LPAR activity as appears to be the case in prostate cancer cells." (PMID 26821052, 2016). "In LNCaP prostate cancer cells, reduced expression of SAM68 altered the expression of an important subset of genes involved in proliferation and apoptosis, including Bcl2L1, Clusterin, cdk2, cdk3, p16INK4, cyclin D1, Par-4, EGF and IGF-1." (PMID 25944080, 2015). "Autocrine expression of EGF and TGF-α affects the autonomous growth of human prostate cancer." (PMID 26042506, 2015). "A data driven, multivariate approach, was used in this study to predict prostate cancer cell survival based on the phosphorylation levels of key proteins in PC3, LNCaP, and MDA-PCa-2b cell lines in response to EGF, IGF1, IL6, TNFα, dihydrotestosterone, and docetaxel treatment." (PMID 24885093, 2014). "Indeed, Craft and colleagues found that castration-resistant xenograft sublines of human prostate cancer cells expressed higher levels of the HER-2/neu, receptor tyrosine kinase activated by EGF." (PMID 23896594, 2013).
prostate carcinoma (continued). "EGF has been shown to enhance the expression or phosphorylation of TIF2, one of the p160 nuclear receptor coactivators, leading to an increase in AR transactivation in prostate cancer cells." (PMID 22922989, 2012). "A new platform of NIR reagents based on IRDye 800CW was developed and used for preparation of IRDye 800CW conjugated EGF which was accepted by NIH database as a molecular imaging and contrast agent for optical visualization of prostate carcinomas in vitro and in mice." (PMID 23144978, 2012). "Here we report that treatment of prostate cancer cells with M-110 or a structurally unrelated PIM kinase inhibitor SGI-1776 increases the expression of MIG6 RNA and protein and inhibits EGF induced activation of the EGFR and the downstream ERK MAPkinase pathway." (PMID 22193779, 2011). "FRS2 and FRS3 suppression in contrast, did not have any appreciable effect on EGF stimulation in either of our prostate cancer cell models." (PMID 22078327, 2011). "Epidermal growth factor stimulates vascular endothelial growth factor expression in a panel of EGFR-positive cancer cells, including glioblastoma, gastric cancer, vulvar squamous carcinoma, bladder cancer and prostate cancer." (PMID 20010942, 2010). "Serum-free media conditioned by the androgen insensitive human prostate cancer cell line DU145 showed immunological transforming growth factor-alpha (TGF alpha) activity, as well as competing activity in epidermal growth factor (EGF) radioreceptor assays (RRA)." (PMID 2223575, 1990). "Interestingly, ASPN-induced phosphorylation of the ErbB family member EGFR at Y845 or Y1173 was undetectable to low in most prostate cancer cell lines assessed, including LNCaP, VCaP, LNCaPenzaR, VCaPenzaR, DU145, and MyC-CaP, especially in comparison with EGF-induced EGFR activation." (PMID 40857406, 2025). "In particular, the interplay among hormones, growth factors such as EGF (epidermal growth factor)- and IGF (insulin-like growth factor)-mediated signaling and even lncRNAs, plays an important role in the pathogenesis of many cancer types such as breast and prostate cancer." (PMID 39199690, 2024). "In prostate cancer, ADAM9 cleaves insulin β-chain, tumor necrosis factor (TNF)-α, transforming growth factor (TGF)-α, gelatin, β-casein, etc., and induces the shedding of epidermal growth factor (EGF), fibroblast growth factor receptor 2 (FGFR2)-IIIB and heparin-binding EGF-like growth factor." (PMID 35740916, 2022). "Additionally, compound 14 at 10 μΜ blocked the activation of Gαi2 in oxytocin-stimulated prostate cancer PC3 cells, and inhibited the migratory capability of DU145 cells overexpressing the constitutively active form of Gαi2, under basal and EGF-stimulated conditions." (PMID 32575572, 2020). "In addition, epidermal growth factor and TALIN2 could be suppressed by miR-132, therefore inhibit prostate cancer metastasis." (PMID 30053878, 2018). "As seen in prostate cancer cells, non-androgens, such as epidermal growth factor (EGF), could increase AR transcriptional activity in bladder cancer cells, which was blocked by AR antagonists." (PMID 28241422, 2017). "This is consistent with a previous report demonstrating that ERK1/2 is not involved in EGF-induced migration of prostate cancer cell line DU14546 and suggests that the PI3K-C2β-regulation of MEK/ERK is involved in steps necessary for cell invasion other than cell migration." (PMID 26983806, 2016). "Moreover, the same tumor stroma overexpressed Epidermal Growth Factor (EGF), FGF, TGF-β, Wnt and ECM related genes, all of which participate in processes that ultimately disrupt interactions mediated by stroma during prostate cancer progression." (PMID 26227631, 2015). "Whether circulating levels of EGF is of clinical relevance to prostate cancer progression has, to our knowledge, not been investigated." (PMID 23861774, 2013).
prostate carcinoma (continued). "Endolysosomal entrapment of the non-toxic targeted toxin EGF-PE24mutΔREDLK followed by activation through enhanced endosomal escape therefore represents a new promising approach for the future treatment of advanced prostate cancer with high efficacy and diminished side effects." (PMID 37859824, 2023). "Interestingly, PTEN/INPP4B loss in non-transformed cells (Mcf10a) potentiates EGF-dependent AKT phosphorylation and invadopodia formation, although it has opposite effects in breast and prostate cancer cells, reducing AKT activation possibly by inhibiting class I PI3K signaling." (PMID 32296634, 2020). "In addition, HVS substantially impaired c-Met-mediated scattering phenotype of DU145 prostate cancer cells in a dose-responsive fashion, while similar treatment doses did not affect EGF-mediated cell scattering, confirming a direct inhibition of the HGF/c-Met signaling pathway." (PMID 27086914, 2016). "Interestingly, HVS did not affect the EGF-mediated scattering in prostate cancer cells, confirming that this oleocanthal-based derivative significantly impaired tumor cell motility and invasiveness mediated only by the HGF/c-Met axis and eliminated the possibility of off-target effects." (PMID 27086914, 2016). "Due to its high and specific cytotoxicity, synergistic treatment with the non-toxic targeted toxin EGF-PE24mutΔREDLK and SO1861 represents a new promising strategy for the future therapy of advanced prostate cancer." (PMID 37859824, 2023). "A central role of ERK1/2, rather than AKT, in EGF-induced EMT induction conforms with earlier reporting but is in contradiction to the published role of AKT in prostate cancer cell lines, nasopharynx carcinoma, and mammary MCF7 cells." (PMID 30261040, 2018). "Consistently in prostate cancer cells perifosine was able to determine a reduction of AKT activity, cell proliferation, and to induce apoptosis after stimulation with 50 ng/ml EGF, although no data concerning EGFR activation were shown so far." (PMID 22590625, 2012). "Culig and colleagues demonstrated that, in human prostate cancer cells, various growth factors including insulin-like growth factor 1 (IGF-I), keratinocyte growth factor (KGF), and epidermal growth factor (EGF) directly activate the AR in the absence of androgens." (PMID 23896594, 2013).
ovarian carcinoma (184 papers, 1991 to 2026). A malignant neoplasm originating from the surface ovarian epithelium. "We have previously shown that loss of E-cadherin contributes to EGF-induced ovarian cancer cell invasiveness." (PMID 27129169, 2016). "We also observed that OP, anti-Neu1 antibody and specific inhibitor MMP-9i treatment of A2780 ovarian cancer cell line blocked Neu1 activity associated with EGF-stimulation of live A2780 cells." (PMID 26932374, 2014). "The effect of EGF on PAF production in ovarian cancer cells was observed using enzyme-linked immunosorbent assay." (PMID 24721622, 2014). "In cancer, STAT3 has been implicated in EGF-mediated EMT in ovarian cancer cell lines and STAT1 has been reported to inhibit angiogenesis in murine fibrosarcoma tumor cells." (PMID 24274066, 2013). "Those authors showed that the gel reduced the invasion of ovarian cancer cells in an immunocompromised mouse model, specifically through the inhibition of signals initiated by epidermal growth factor and the reduced expression of proteins linked to metastasis (such as Rac1 protein)." (PMID 39255313, 2024). "In CAOV3 ovarian cancer cell lines, extracellular EGF caused a significant rise in the PAF released from 0.5 ng/ml to 100 ng/ml; while in SKOV3 ovarian cancer cell lines, ext racellular EGF caused a significant rise in the PAF release from 1 ng/ml to 100 ng/ml." (PMID 24721622, 2014). "Ovarian cancers that express increased concentrations of the EGF receptor are associated with poor survival and both TGFα and EGF have been shown to stimulate growth of ovarian cancer cells in culture." (PMID 11875715, 2002). "In addition, the bidirectionally crosstalk between PAF and epidermal growth factor (EGF) suggest that PAF induced by EGF via cytosolic phospholipase A2 could cause the acts on the PAF-receptor to promote tumor progression in the ovarian cancer." (PMID 29383198, 2017). "In addition, we report that the JAK2/STAT3 pathway is required to sustain EGF-induced EMT-associated phenotypes in ovarian cancer cells, indicating that in EGF-driven ovarian tumours JAK2/STAT3 signalling may be critical in regulating metastasis." (PMID 19088723, 2009). "Impact statement This work provides direct evidence that MMP9 mediates EGF-driven membrane protrusions and promotes ovarian cancer cell adhesion to mesothelial extracellular matrices." (PMID 41732872, 2026). "Together, these results provide direct evidence that MMP9 mediates EGF-driven membrane protrusions and promotes ovarian cancer cell adhesion to mesothelial extracellular matrices." (PMID 41732872, 2026). "Matrix metalloproteinase-9 (MMP9), an extracellular endopeptidase, is upregulated by Epidermal Growth Factor (EGF) signaling and associated with ovarian epithelial cancer progression." (PMID 41732872, 2026). "-Pf-2545920 and MCI-030 inhibitors suppress ovarian cancer cell growth by inducing cell cycle arrest and apoptosis through the dual inhibition of Wnt/β-catenin and EGF-mediated RAS/MAPK/AKT signaling pathways." (PMID 41179677, 2025). "EGF-modified emodin micelles are characterized for their physical and chemical properties, showing enhanced uptake and antiproliferative effects in ovarian cancer (SK-OV-3) cells." (PMID 40490812, 2025). "In particular, TAM‐derived EGF has been shown to sustain the formation of ascetic spheroids during metastasis by facilitating their interaction with ovarian cancer cells, which is mediated by αMβ2 integrin and intercellular adhesion molecule 1 (ICAM‐1)." (PMID 38411356, 2024). "It has been reported that the expression of HE4 in ovarian cancer is related to epidermal growth factor activity and pointed out that HE4 has a potential interaction with epidermal growth factor receptor (EGFR) or other cell surface receptors." (PMID 38742362, 2024).
ovarian carcinoma (continued). "The expression of COX-2 in ovarian cancer cells is regulated by various cytokines, such as EGF, vitamin D, IL-1β, which can stimulate the proliferation, migration, and angiogenesis of ovarian cancer cells." (PMID 38764576, 2024). "Additional research demonstrated that GnRH2 treatment inhibited mitogenic effects of EGF in ovarian cancer cells." (PMID 38260130, 2023). "EMT was induced in the ovarian cancer cell line CAOV3 by treating it with EGF (10 ng/mL) for 96 h following 24 h of serum deprivation." (PMID 38031074, 2023). "In ovarian cancer cells, this translocation is induced by epidermal growth factor (EGF) stimulation." (PMID 36815702, 2023). "It has been shown that p38 MAPK participates in epidermal growth factor-induced Snail expression in human ovarian cancer cells." (PMID 37143106, 2023). "Specifically, TAM in ovarian cancer activates EGFR through secreted EGF and up-regulates VEGF/VEGFR signals in peripheral tumor cells, supporting tumor cell proliferation and migration." (PMID 37005667, 2023). "In ovarian cancer, EGR-1 mediated epidermal growth-factor-induced downregulation of E-cadherin expression via Slug in ovarian cancer cells." (PMID 36233659, 2022). "In ovarian carcinoma cells in 3D collagen, EGFR and MT1-MMP colocalize with caveolae prior to activation and stimulation with EGF disrupts their association and leads to MT1-MMP internalization." (PMID 35819726, 2022). "TAMs release epidermal growth factor (EGF) in ovarian cancer, and directly activate the EGFR-ERK pathway." (PMID 35565348, 2022). "In ovarian cancer cells, Cx43 gene knockout promoted EGF-induced cell proliferation, but overexpression of Cx43 decreased EGF's influence on ovarian cancer cell proliferation." (PMID 35783340, 2022). "In order to stimulate pronounced protrusions in these cells, we stimulated the cells with the epidermal growth factor (EGF), a known chemoattractant of ovarian cancer cells." (PMID 34958986, 2022). "In laboratory experiments using ovarian cancer and head and neck cancer cell lines, EGF promoted TAMS and metastasis." (PMID 35780243, 2022). "In all, our results suggest that CA inhibits ovarian cancer progression and metastasis in vivo and in vitro and inhibits EGF-induced EMT processes through the PI3K/AKT signaling pathway." (PMID 35645793, 2022). "Recent reports have shown that CAFs in spheroids that receive TGF-β signaling from ovarian cancer secrete epidermal growth factor and induce integrin α5 expression in ovarian cancer, promoting adhesion to the peritoneum." (PMID 36233262, 2022). "Studies have also shown that the levels of serum EGF were elevated in various types of cancer, such as lung, colorectal, esophageal, liver, and ovarian cancers." (PMID 34804932, 2021). "Human TAMs secrete epidermal growth factor (EGF) to potentiate the invasiveness of ovarian cancer cells." (PMID 34359674, 2021). "Given the varying response of ovarian cancer cells to growth factor stimulation, we also compared spheroid efficiency using standard 2-D media, which contains serum, but lacks EGF and FGF." (PMID 33445692, 2021). "Contrarily, BDNF administration resulted in changes in serum epidermal growth factor (EGF) concentrations, which facilitated the migration of lung and ovarian cancer cells." (PMID 34395067, 2021). "For example, HIF-1 mediates epidermal growth factor-induced down-regulation of E-cadherin expression and cell invasion in human ovarian cancer cells." (PMID 33768003, 2021). "It has also been shown that the expression of MMP-9 and TIMP-1 induced by the epidermal growth factor (EGF) in ovarian cancer cell lines results in increased migration and mass spread induced by EGF." (PMID 34572929, 2021). "TGFB1 does not induce SNAI1 expression in OVSAHO or OVCAR8; for this reason, ovarian cancer cell lines were treated with EGF." (PMID 33806868, 2021).